IL5 (interleukin 5)
Diseases named in the same sentence as IL5 in open-access papers (continued):
Sharing a sentence is not in itself a finding about the gene and the disease.
infertile (4 papers, 2009 to 2021). "In contrast, IL-1β, IL-4, IL-5, IL-6, IL-10 mRNA expression levels were significantly higher (P < 0.05) in cells obtained from CT-positive infertile women compared to controls and CT-positive fertile women." (PMID 19698128, 2009). "Significant higher expression (P < 0.05) of Interferon-gamma, IL-12, IL-23 and GM-CSF were found in Inc-stimulated CD4 enriched cervical cells of CT-positive fertile women and contrastingly high IL-1 Beta, IL-4, IL-5, IL-6 and IL-10 levels were found in CT-positive infertile women." (PMID 19698128, 2009). "Overall our data shows that CT IncB and IncC are able to upregulate expression of cytokines, namely interferon-gamma, IL-12, IL-23 and GM-CSF in CT-positive fertile women while expression of IL-1 Beta, IL-4, IL-5, IL-6 and IL-10 were upregulated in CT-positive infertile women." (PMID 19698128, 2009). "In this study we detected high levels of IL-1β, IL-6, IL-4, IL-5 and IL-10 in IncB or IncC-stimulated CD4+ T cells in CT-positive infertile women compared to CT-positive fertile women and controls." (PMID 19698128, 2009). "Recent studies have shown that several cytokines, including IFN-γ, TNF-α, IL-2, IL-4, IL-5, and IL-10, were produced by immunocompetent cells in the blood from PCOS with infertility in vitro, which might be involved in chronic inflammation." (PMID 30988342, 2019).
inflammatory skin disease (4 papers, 2020 to 2025). Inflammatory skin disorders covers a broad category that includes many conditions ranging in severity, from mild itching to grave medical health complications These disorders are common in people of all ages and races. "T helper 2 (Th2)-mediated dermatoses are inflammatory skin diseases driven by CD4+ Th2 cells that produce interleukin (IL)-4, IL-5, IL-13, and IL-31, promoting immunoglobulin E (IgE) class switching, eosinophil recruitment, mast cell degranulation, and pruritus." (PMID 41226755, 2025). "When the epidermal barrier of the skin is damaged by physical or chemical stimuli, many cytokines (IL-1β, IL-6, TNF-α, IL-5, and TSLP) and chemokines (MCP-1, RNATES, TARC, MDC, CXCL8, and CXCL10) are expressed in stimulated keratinocytes to promote the progression of inflammatory skin diseases." (PMID 36670888, 2022).
intestinal inflammation (4 papers, 2015 to 2024). "JunB is a transcription factor that promotes the expression of Th2 cytokines IL-4 and IL-5, Therefore, blocking the production of IL-4 and IL-5 may be one of the targeted mechanisms of Th-cell associated gastroenteritis and IBD." (PMID 39185411, 2024). "Altogether, these data demonstrate that GM-CSF and IL-5 promote the survival of peripheral eosinophils, but only GM-CSF promotes their activation and inflammatory cytokine production, revealing one of the key colitogenic effects of GM-CSF during chronic intestinal inflammation." (PMID 26200014, 2015).
lupus nephritis (4 papers, 2014 to 2024). Glomerulonephritis in the context of systemic lupus erythematosus. "A recent study with lupus nephritis patients discovered an increase in urinary eosinophils along with the detection of eosinophil cationic protein and IL-5." (PMID 35444658, 2022). "The aim of this study was to investigate eosinophiluria, urinary eosinophil cationic protein (uECP) and urinary IL-5 (uIL-5) in patients with Lupus Nephritis." (PMID 25520739, 2014). "Interestingly, urinary IL-5 and eosinophiluria were increased in patients with lupus nephritis, suggesting IL-5 mediated recruitment of eosinophils occurs in nephritis patients." (PMID 35444658, 2022). "IL-9 and IL-10 showed a significant positive correlation with IL-25 in all 17 SLE patients with lupus nephritis, whereas a significant negative correlation was observed with IL-5 and IL-6." (PMID 31697750, 2019). "IL-10 showed a significant positive correlation with IL-25 in all 47 SLE patients without lupus nephritis, whereas a significant negative correlation was observed with IL-5." (PMID 31697750, 2019). "Thus, the aim of this research is to determine the plasma levels of IL-25 and Th2-associated cytokines (IL-4, IL-5, IL-6, IL-9, IL-10, IL-13) in SLE patients with (SLE-LN) and without lupus nephritis." (PMID 31697750, 2019).
mastitis (4 papers, 2020 to 2025). Inflammation of breast tissue during lactation or postpartum due to an obstructed duct or infection. "The SCC and levels of generated cytokines (interleukin (IL)-1, IL-2, IL-4, IL-5, IL-6, IL-8, IL-10, and IL-12) in milk increase in both naturally occurring and experimentally induced mastitis." (PMID 40303387, 2025). "Th1/Th2 polarisation shifted towards Th2 due to the increase in IL‐4 and IL‐5 concentrations in NP cows that developed mastitis in the postpartum period." (PMID 39792067, 2025). "In cases of postpartum diseases, Th1/Th2 polarisation shifted towards Th2 due to the increase in IL‐4 and IL‐5 concentrations in cows that performed NP and developed mastitis in the postpartum period." (PMID 39792067, 2025).
parasite (4 papers, 2012 to 2023). "Indeed, in type-2-skewed responses, such as some parasite infections in the gut, IL-25 clearly drives the inflammation upstream of IL-4, IL-5, and IL-13 and therefore acts as a pro-inflammatory cytokine." (PMID 22539101, 2012).
pertussis (4 papers, 2010 to 2025). A contagious bacterial respiratory infection caused by Bordetella pertussis. "In addition, low amounts of IFN-γ and IL-5 were only produced by the spleen cells of TRIF-deficient mice immunized with whole cell pertussis vaccine." (PMID 21203418, 2010). "The acellular pertussis vaccines induced a mixed cytokine profile showed elevated IFN-γ production (associated with IL-2), low IL-4, and more abundant IL-5 production." (PMID 37574522, 2023).
Pleural effusion (4 papers, 2022 to 2025). The presence of an excessive amount of fluid in the pleural cavity. "A clinical observational study demonstrated a significant correlation between IL-5 levels in pleural effusions of LUAD patients and the number of malignant cells present." (PMID 40136462, 2025). "A particularly notable example is Th17 cells, which correlated strongly negatively with the levels of IL-5, IL-6 and IL-8 in pleural effusion (r = -0.6, r = -0.7 and r = -0.7, respectively and p<0.05 for each)." (PMID 39737183, 2024). "Along with eosinophils, macrophages are the major infiltrates in pleural effusions in WT mice and are the main cells present in Il-4rα-/-/Il-5-/- mice." (PMID 36353644, 2022).
pneumonitis (4 papers, 2020 to 2025). An inflammatory process affecting the lung parenchyma. "However, the role of IL-5 and IL-10 in lung injury associated with pneumonitis remains uncertain." (PMID 40963607, 2025). "This observed difference was driven primarily by endocrine (n = 7) and other irAEs (n = 11) for IL-5; dermatologic (n = 5), enterocolitis (n = 6), and endocrine irAEs for IL-6; and pneumonitis (n = 5) for TNF-α (P < 0.05)." (PMID 39403935, 2024). "The actual mechanism as to how IL-5, a Th2 cytokine and a powerful eosinophil activator and recruiter, may be involved in lung injury of pneumonitis is uncertain." (PMID 38226621, 2024).
Pulmonary TB (4 papers, 2010 to 2025). "One study, conducted in 2020, examined the systemic level of serum IL-5 in active pulmonary TB, and its alteration across different stages of treatment." (PMID 40431146, 2025). "Cytokines such as IL-1, sIL-2R, TNF-α, IL-5, IL-6, and IFN-γ play important roles in pulmonary tuberculosis patients, and their elevated levels may be associated with disease severity and inflammatory status." (PMID 39432654, 2024). "The findings indicated that IL-5 is systemically reduced in patients with active pulmonary TB, unlike LTBI and healthy controls." (PMID 40431146, 2025).
Splenomegaly (4 papers, 2009 to 2018). Abnormal increased size of the spleen. "IL-33 plays a major role in Th2 responses by inducing Th2 cytokines IL-4, IL-5, IL-13, splenomegaly, eosinophilia, and allergy." (PMID 23112799, 2012). "Levels of circulating IL-5 were significantly higher in the children who presented with hepatomegaly-only or hepatosplenomegaly, compared with the children who had splenomegaly-only." (PMID 19149774, 2009). "Indeed, Tir8/Sigirr-deficient mice showed hyper responsiveness to IL-33 with increased serum levels of IL-5 and IL-13, splenomegaly, lung inflammation, and exacerbated Th2 responses in OVA-induced allergic pulmonary inflammation." (PMID 23112799, 2012). "Similarly, the splenomegaly of Il-5 Tg mice was also reversed by Eos depletion." (PMID 29327730, 2018). "Co-application of Ad.pIXgp70 with Ad.IL5, Ad.IL6 or Ad.IL23 resulted in improved protection with high control over FV-induced splenomegaly and reduced viral loads." (PMID 24349306, 2013).
toxocariasis (4 papers, 2021 to 2025). A parasitic infection caused by worms found in domestic animals. "In contrast, in toxocariasis, Th2 cells are involved; they secrete IL-4, IL-5, IL-9, IL-10, and IL-13 and promote type 2 immunity, characterized by high antibody titers." (PMID 40943043, 2025).
toxoplasmosis (4 papers, 2009 to 2023). A parasitic disease contracted by the ingestion or fetal transmission of toxoplasma gondii. "Toxoplasmosis has a strong effect on the concentration of various cytokines, especially interleukin (IL)-10, IL-5, IL-6, and transforming growth factor beta (TGF-β)." (PMID 34583758, 2021). "However, Filisetti and Candolfi revealed an IL-5 induced increase in IL-12 production in toxoplasmosis." (PMID 19478959, 2009). "In our study, in the course of toxoplasmosis the levels of TNF-α and IL-12 did not change, whereas the concentration of IL-5 increased." (PMID 19478959, 2009).
Type I hypersensitivity reaction (4 papers, 2021 to 2024). "The Th2 cells, through IL production, are responsible for a type I hypersensitivity reaction, with eosinophils being involved via IL-5, which controls the recruitment and function of eosinophils in target tissues." (PMID 36499410, 2022). "In type I hypersensitivity reactions, low concentrations of the allergen (via inhalation or exposure in the gastrointestinal tract) presented in the presence of interleukin (IL)-4, IL-5, IL-9, and IL-13 are responsible for the dominant Th2 response." (PMID 34099042, 2021). "Eosinophils and Interleukin (IL)-5 are involved in a hypersensitivity type I reaction." (PMID 36499410, 2022).
uveitis (4 papers, 2022 to 2024). An inflammatory process affecting a part of or the entire uvea. "Traditionally, pro-inflammatory Th1/Th17 immune responses are hallmark features of uveitis, while a Th2 response characterized by high levels of IL-4, IL-5, and IL-13 is associated with UC." (PMID 37396905, 2023). "IL-5, IL-10, and IL-13 showed 3-fold or more significant elevations in OT than in non-OT uveitis patients." (PMID 35646978, 2022). "It is interesting to note that IL-5 and IL-13 were almost undetectable in non-OT uveitis in our study." (PMID 35646978, 2022). "Moreover, expression of IL-5, IL-9, IL-10, IL-13, and PDGF-AA, were significantly increased in the OT group alone, compared with the non-OT uveitis and control groups." (PMID 35646978, 2022).
vitamin D deficiency (4 papers, 2013 to 2023). A nutritional condition produced by a deficiency of VITAMIN D in the diet, insufficient production of vitamin D in the skin, inadequate absorption of vitamin D from the diet, or abnormal conversion of vitamin D to its bioactive metabolites. "D-dimer and IL-5 levels were higher in patients with vitamin D deficiency than in those in the normal and vitamin D insufficient groups (P < 0.05), while CD8 + T cell numbers were significantly lower in the vitamin D deficient group (P > 0.05)." (PMID 37705107, 2023). "The levels of D-dimer and IL-5 were higher in patients with vitamin D deficiency than in those in the vitamin D normal and insufficient groups, while the number of CD8+ T cells was significantly lower in the vitamin D deficient group." (PMID 37705107, 2023). "Vitamin D deficiency shifts this system toward a pro-inflammatory state that favors Th1 and Th17 activation and increased expression of TNF, IFNγ, and IL-17, as well as elevated expression of pro-inflammatory Il-4, IL-5 and IL-13, and gut barrier dysfunction." (PMID 32093192, 2020). "As observed previously with higher doses of OVA/Alum, vitamin D deficiency enhanced the capacity of ADLN cells to proliferate and secrete cytokines like IL-4, IL-5, IL-10 (data not shown), but not IL-6, IL-17, TNF or IFNγ (data not shown)." (PMID 23826346, 2013). "Again, vitamin D deficiency enhanced the capacity of ADLN cells to proliferate and secrete cytokines like IL-5 and IL-13 (data not shown)." (PMID 23826346, 2013).
vitiligo (4 papers, 2018 to 2024). Generalized well circumscribed patches of leukoderma that are generally distributed over symmetric body locations and is due to autoimmune destruction of melanocytes. "To check for the possible signs of systemic inflammation, we measured the concentration of inflammation-associated cytokines (TNF-α, IFN-γ, IL-1b, IL-1Ra, IL-2, IL-5, IL-6, CXCL8, CXCL10, G-CSF, and GM-CSF) in the plasma of vitiligo patients." (PMID 30515176, 2018). "Remarkably, many of the increased proteins in patients achieving F-VASI50 were interleukins such as IL-20 and Th2 linked cytokines IL-5 and IL-13 for which no major role in vitiligo has previously been described." (PMID 38715599, 2024). "Pro-inflammatory cytokines such as tumor necrosis factor alpha (TNF-α), interleukin-6 (IL-6), interleukin-8 (IL-8), interleukin-1β (IL-1β), IFN-γ, and some anti-inflammatory cytokines such as interleukin-5 (IL-5) and IL-10 are increased in patients with active vitiligo." (PMID 36439174, 2022). "Meanwhile, there is mounting evidence that the immunological milieu of vitiligo is also characterized by cytokines connected to other Th2 cell responses, such as IL-4, IL-5, IL-10, IL-13, and IL-31, rather than just Th1 cells and related cytokines (IFN-γ, TNF-α, and IL-2)." (PMID 38695020, 2024).
appendicitis (3 papers, 2019 to 2025). Acute inflammation of the vermiform appendix. "We discovered that preoperative serum levels of IFN-γ, IL-5, IL-6, IL-8, and IL-10 hold diagnostic value in staging pediatric acute appendicitis." (PMID 40150581, 2025). "In the appendicular lavage fluid, the higher levels of IL-5 were observed in the phlegmonous appendicitis group (p = 0.056)." (PMID 36499410, 2022). "Here, we propose the concept of appendicular lavage and use it to study the levels of the Th2 cytokines IL-4, IL-5, and IL-9 in patients with a clinical diagnosis of acute appendicitis." (PMID 31772507, 2019). "When comparing phlegmonous appendicitis values with those of NPA, the difference was significant (p = 0.01): IL-4 (48.3 vs. 21.3 pg/mL), IL-5 (29.2 vs. 8.0 pg/mL), and IL-9 (34.1 vs. 16.6 pg/mL)." (PMID 36499410, 2022). "Lack of eosinophils and IL-5 blood concentrations before clinical appendicitis, as this would serve as a reference and will enable us to follow the dynamic of blood changes." (PMID 36499410, 2022). "Differences in IL-4, IL-5, and IL-9 in AL fluid were found between the 3 study groups and especially significant between phlegmonous and negative appendicitis." (PMID 31772507, 2019). "The difference was more pronounced when comparing phlegmonous appendicitis with nonpathological appendicitis (p = 0.01) for IL-4 (48.3 vs. 21.3 pg/mL), IL-5 (29.2 vs. 8.0 pg/mL), and IL-9 (34.1 vs. 16.6 pg/mL)." (PMID 31772507, 2019).
ascariasis (3 papers, 2016 to 2025). An infection that is caused by the roundworm Ascaris lumbricoides, many cases of which remain asymptomatic. "Human ascariasis is characterized by a Th2 and regulatory immune response, although innate production of IL-5, IL-6 and TNF-α seems to play crucial role in the pathogenesis of experimental larval ascariasis." (PMID 26814713, 2016).
B cell lymphoma (3 papers, 2012 to 2022). "A previous study showed dysregulated circulating cytokines (such as IL5, IL13, TNF, etc.)were correlated with B-cell non-Hodgkin lymphoma." (PMID 35452413, 2022).
bipolar disorder (3 papers, 2015 to 2024). A disorder of the brain that causes unusual shifts in mood, energy, activity levels and the ability to carry out day-to-day tasks. "Eosinophil number, and in particular eosinophil lymphocyte ratio has been considered as a marker of alcohol use in patients with bipolar disorder may relate to increased IL-5 and TNF levels, and production and release of eosinophils from bone marrow." (PMID 38545104, 2024).
chronic bronchitis (3 papers, 2024 to 2025). A type of chronic obstructive pulmonary disease characterized by chronic inflammation in the bronchial tree that results in edema, mucus production, obstruction, and reduced airflow to and from the lung alveoli. "Exacerbations of chronic bronchitis are often accompanied by significant airway eosinophilia, characterized by the release of inflammatory mediators including interleukin-4 (IL-4), interleukin-5 (IL-5), and interleukin-13 (IL-13)." (PMID 39361621, 2024). "Additionally, smokers without chronic obstructive bronchitis exhibit plasma cells that express IL-4 and IL-5, with IL-4 promoting mucus secretion and exacerbating lung inflammation." (PMID 40997602, 2025).
chronic eosinophilic leukemia (3 papers, 2018 to 2025). "The activity of interleukin‐5 (IL‐5) is known as a growth factor for eosinophils, and overexpression of IL‐5 was observed in a chronic eosinophilic leukemia murine model." (PMID 41208700, 2025). "The one disease variant for which IL-5 targeting should not be considered an option is chronic eosinophilic leukemia (CEL) with well-documented underlying cytogenetic rearrangements, most commonly the FIP1L1/PDGFRA (F/P) fusion gene." (PMID 29682504, 2018).
chronic pancreatitis (3 papers, 2020 to 2025). A chronic inflammatory process causing damage and fibrosis of the pancreatic parenchyma. "When compared to patients with chronic pancreatitis, IL‐5 was significantly increased in serum of patients with PDAC." (PMID 38686549, 2024). "In a RAS-driven model of chronic pancreatitis and pancreatic tumor formation, IL5 expression increased in early lesions, followed by increased IL5R-α expression, consistent with the idea that the β-common ligand IL5 can play roles in solid tumors, which requires further study." (PMID 40075752, 2025).
diabetic nephropathy (3 papers, 2019 to 2025). "IL-5 mRNA levels are also increased in patients with diabetic nephropathy compared to those without diabetic nephropathy." (PMID 39347908, 2025).
dysplasia (3 papers, 2024 to 2025). A usually neoplastic transformation of the cell, associated with altered architectural tissue patterns. "In laboratory experiments, isolated cells expressing CCL20 and CCR4, stimulated by IL-5 and IL-7, demonstrated an increased ability of CD8+ T cells to penetrate dysplastic cells, thereby improving therapeutic efficiency in fighting dysplasia." (PMID 39273632, 2024). "However, our inverse associations with dysplasia are consistent with a previous study that found that IL‐2, IL‐5, IL‐8, IL‐10, IL‐13 and TNF‐alpha tend to be downregulated in low‐grade/moderate dysplasia of the pancreas compared to serous cystadenoma without dysplasia." (PMID 39482824, 2025).
Fasciola infection (3 papers, 2012 to 2025). "Moreover, the depletion of eosinophils during experimental fasciolosis was associated to a decreased production of IL-4, IL-5 and IFNγ, suggesting that in the absence of eosinophils the Th2 or Th1 immune responses are impaired." (PMID 33042162, 2020). "In a mouse study with experimental Fasciola infection, spleen cells from BALB/c exhibited a Th2 response, producing high levels of the cytokines IL-4 and IL-5, and low levels of IFN-gamma and IL-2." (PMID 22938392, 2012).